GAPDH (glyceraldehyde-3-phosphate dehydrogenase)
Diseases named in the same sentence as GAPDH in open-access papers (continued):
Sharing a sentence is not in itself a finding about the gene and the disease.
melanoma (45 papers, 2001 to 2025). A malignant, usually aggressive tumor composed of atypical, neoplastic melanocytes. "In this study, we showed for the first time that cerium oxide nanoparticles induced thiol oxidation of the enzyme GAPDH in A375 melanoma cells, resulting in loss of the enzymatic activity and a decrease in intracellular lactate formation." (PMID 38512909, 2024). "We showed that incubation of both melanoma cells and normal human epidermal melanocytes were susceptible to GAPDH inhibition by usage of the GAPDH inhibitor heptelidic acid (HA)." (PMID 38512909, 2024). "Finally, to prove that the loss of viability initiated by CNP in A375 in melanoma cells is partially due to inhibition of GAPDH and subsequent insufficient energy supply, we wanted to see if supplementation with lactate rescues CNP induced toxicity." (PMID 38512909, 2024). "However, the normal (healthy cells) remained viable, but GAPDH inhibition of A375 melanoma cells led to an almost total loss of viability." (PMID 38512909, 2024). "Therefore, we aimed to study for the first time the anti-tumor activity of the GAPDH inhibitor GP-2250 in BRAF-mutated melanoma cell lines and benign melanocytes." (PMID 37895015, 2023). "In summary, addition of 300 μM CNP to low doses of HA (i.e. 0.1 and 0.25 μM, respectively) increased the effect of the GAPDH inhibitor on melanoma cell viability, whereas the viability of melanocytes was unaffected by additional CNP administration." (PMID 38512909, 2024). "The CNP induced decrease in melanoma cell viability can be mimicked with the administration of the GAPDH inhibitor heptelidic acid (HA)." (PMID 38512909, 2024). "This makes it likely that CNP exhibit their selective toxic effect on melanoma cells partially by inhibition of glycolysis via the observed thiol oxidation of the enzyme GAPDH." (PMID 38512909, 2024). "Upon CNP mediated inhibition of GAPDH in melanoma cells, the formation of pyruvate and the subsequent reduction of pyruvate to lactate should be decreased in these cells." (PMID 38512909, 2024). "It was suggested that the simultaneous production of two isoenzymes of glyceraldehyde-3-phosphate dehydrogenase not only stimulates glycolysis in melanoma cells, but also alters the induction of apoptosis, which involves only the somatic enzyme." (PMID 37711387, 2023). "This study assessed the growth and GAPDH inhibitory effects of orally administered HA on extraintestinal melanoma using in vitro cell proliferation assay and in vivo homograft melanoma mouse model." (PMID 35459092, 2022). "In this study, the in vitro and in vivo HA treatments downregulated GAPDH activity in melanoma cells, suggesting that the extraintestinal tumor-suppressive effects of HA were mediated by GAPDH inactivation." (PMID 35459092, 2022). "We demonstrated that HA derived from A. oryzae HA exerts antiproliferative effects by inhibiting GAPDH in melanoma-derived B16F10 cells." (PMID 35459092, 2022). "This study suggests that orally administered HA was absorbed in the gastrointestinal tract, reached the cancer cells transplanted in the skin, and inhibited GAPDH activity, thereby inhibiting the growth of extraintestinal melanoma cells." (PMID 35459092, 2022). "MIST also faithfully recovered the gene expression spatial pattern for GAPDH in the melanoma tissue sample after denoising." (PMID 36376296, 2022). "For the housekeeping gene GAPDH, 20 semitryptic peptides were identified in the melanoma cell line M14 and over 10 semitryptic peptides in the cell lines CCRF-CEM, Colo-205, MCF-7, and RXF-393." (PMID 34070654, 2021). "We further compared the relative gene expression ratios of target genes LRP1, ACTB and GAPDH across 13 melanoma cell lines estimated by qRT-PCR or ddPCR." (PMID 31567589, 2020). "It should also be noted that in general the average expression of ACTB and GAPDH the skin samples is fairly low compared to their expression in the melanoma samples." (PMID 31567589, 2020).
melanoma (continued). "We investigated the expression stability of ACTB and GAPDH across four melanoma cell lines; FM3, FM82, FM88 and FM92." (PMID 31567589, 2020). "The distribution of PTCH1 gene expression level for all TCGA patients compared to genes known to be well expressed in melanoma (GAPDH, ACTB, MITF) indicates that PTCH1 is well expressed in primary and metastatic samples." (PMID 32526884, 2020). "The metastatic melanoma samples exhibited significantly higher expression levels of FOXM1 compared to the primary melanoma samples when the expression was normalized to GAPDH (p = 0.004)." (PMID 26640950, 2015). "WLS shRNAs also enhance the proliferation of both A2058 (85.6%, p = 0.0014) and MEL624 cells (37.1%, p = 0.0019) compared to control and GAPDH shRNAs indicating that WLS negatively regulates the proliferation of multiple melanoma cell lines." (PMID 23129487, 2012). "The use of GAPDH as a reference gene in the majority of tumour types, including melanoma, has recently been challenged." (PMID 21324211, 2011). "Despite GAPDH was widely used in the past, its use as a reference gene has recently been challenged in the majority of tumor types, including melanoma, liver, bladder, renal cancer, prostate, gastroesophagic and pancreatic cancer, and colon adenocarcinoma." (PMID 19014639, 2008). "Next, we wanted to test whether a pharmacological inhibition of GAPDH also lowers cell viability in melanoma cells (proof of principle)." (PMID 38512909, 2024). "The fact that incubation with an GAPDH inhibitor led to a stronger decrease in viability of tumor cells than of normal (healthy) cells supports the hypothesis that melanoma cells are more prone to glycolysis than normal cells." (PMID 38512909, 2024). "Since GP-2250 is a GAPDH inhibitor, the substance may be a promising combination therapy for tumors presenting the Warburg effect, such as melanoma." (PMID 37895015, 2023). "Enhanced glycolysis (Warburg effect) driven by the BRAF oncogene, dysregulated GAPDH expression, and activation of the PI3K/AKT/mTOR signaling pathway may significantly contribute to the resistance-targeted therapy of BRAF-mutated melanomas." (PMID 37895015, 2023). "Upregulation of GAPDH → bypassing senescence induced by the melanoma oncoprotein BRAFV600E." (PMID 37190033, 2023). "Therefore, GAPDH activity in HA melanoma cells was assessed, and it was observed that HA inhibited the GAPDH activity in a concentration-dependent manner." (PMID 35459092, 2022). "In advanced melanoma, there is an increase in aerobic glycolysis; glyceraldehyde-3-phosphate dehydrogenase (GAPDH) and pyruvate kinase M2 (PKM2) are overexpressed in melanoma compared with nevi, and their expression increases from the radial growth stage to metastatic melanoma." (PMID 36143291, 2022). "This protein has unusual properties different from its somatic isoenzymes and could significantly influence metabolism and proliferation, and the presence of GAPDHS confers a number of unusual properties compared with those of GAPDH in melanoma." (PMID 34249897, 2021). "By comparing the relative expression ratios of target genes LRP1, ACTB and GAPDH across two melanoma cell lines estimated using an RNAseq approach and a qRT-PCR-based approach, we show that indeed we obtain similar relative gene expression levels of the target genes." (PMID 31567589, 2020). "The expression of ACTB and GAPDH in 13 primary melanomas was investigated by qRT-PCR." (PMID 31567589, 2020). "In addition, GAPDH levels are altered in some defective and transfected cell lines and have also been reported in patients with melanoma." (PMID 32089674, 2020). "The highest c-myc gene expression compared to GAPDH was found in melanoma metastases (17.5%)." (PMID 11139316, 2001).
melanoma (continued). "The treatment of melanoma cells and melanocytes with the GAPDH inhibitor heptelidic acid (HA) decreased viability to a much higher extent in the cancer cells than in the studied normal (healthy) cells, highlighting and supporting the important role of GAPDH in cancer cells." (PMID 38512909, 2024). "Thus, consistent with the reported dependency of SELF melanoma associated antigen expression upon AIRE51, 52, GAPDH, TYRP2 and CSDE1, three well-characterized SELF proteins, are regulated by AIRE in B16-OVA cells, but expression of stably transfected, CMV-driven OVA protein was independent of AIRE." (PMID 39606441, 2024). "Hence, it appears reasonable to evaluate the effect of GAPDH inhibitors in melanoma." (PMID 37895015, 2023). "Notably, the reduction in GAPDH enzymatic activity and cell density was parallelly shifted, indicating that the growth-suppressive function of HA was mediated by the inhibition of GAPDH activity in melanoma cells." (PMID 35459092, 2022). "Second, GAPDHS is known to exhibit higher stability than GAPDH, which may cause the enzyme to hinder the translocation of GAPDHS into the nucleus to induce cell apoptosis that may play a role in the malignant phenotype of melanoma cells." (PMID 34249897, 2021). "Multiple sections of each tumor were analyzed (minimum n = 3; maximum n = 6 per tumor), and inter- and intra-tumor variation in gene expression was evaluated to assess if ACTB and GAPDH could qualify as reference genes in qRT-PCR-based analysis of gene expression in melanoma tissue samples." (PMID 31567589, 2020). "Moreover, although most tumors exhibit a preferential switch to glycolysis, ceramide may reduce GAPDH expression targeting the “Warburg effect”, as observed in melanoma cells." (PMID 26811497, 2016). "In this study, we have analyzed the intra- and inter-tumor expression stability of the two commonly used reference genes, ACTB and GAPDH, in 13 FFPE melanoma samples by qRT-PCR." (PMID 31567589, 2020). "Overexpression of Akt impairs mitochondrial function, promotes glycolytic metabolism with upregulation of glyceraldehyde-3-phosphate dehydrogenase (GAPDH), and converts radial growth (i.e., noninvasive) melanoma into vertical growth (i.e., invasive) melanoma." (PMID 28137309, 2017). "In our search for safe immunotherapy for advanced melanoma, we used experimental DC vaccines loaded with different peptides of LLO or GAPDH virulence factors of Listeria, to examine their anti-tumour potential against metastatic B16OVA melanoma." (PMID 26942874, 2016). "mRNA from melanoma B16F10 cells expressing the MAAs gp100 and TRP-2 cells was included as a positive control and GAPDH was used for normalisation." (PMID 22506061, 2012). "In the melanoma dataset, STModule identifies similar components from the two samples, including cancer cells (I), transition areas (II), lymphoid tissue (III; CD74, CD52, MS4A1), immune activities (IV-VI), CAFs, and melanocytes (GAPDH)." (PMID 40033360, 2025). "Although the UPR and GAPDH responses were less prominent in the melanoma patients, these functions in PBMCs were demonstrated to react to BCG despite the highly different variables represented by the melanoma vs. the NMIBC therapy groups." (PMID 40864805, 2025). "Here we addressed the question of whether CNP, in addition to its induction of mitochondrial dysfunction, has direct impact on GAPDH, and whether this does contribute to the selective toxicity of CNP in melanoma cells." (PMID 38512909, 2024). "Interestingly, immunoprecipitation of proteins from melanoma cell extracts with the anti-GAPDS antibodies allowed isolation of a tetrameric protein containing both subunits of t-GAPDS and subunits of somatic GAPDH." (PMID 37711387, 2023).
melanoma (continued). "The expression of MCAM was significantly 25 times higher in B16F10 melanoma cells compared to TS/A carcinoma cells (Ct value for MCAM expression in B16F10 was 24.7 and for TS/A, it was 30.9; Ct value for GAPDH expression in B16F10 was 19.2 and for TS/A, it was 20.7)." (PMID 32204304, 2020). "We show that housekeeping genes like GAPDH do not qualify as stand-alone normalizers of genes expression in melanoma." (PMID 31567589, 2020). "Here, we determine the level of B16.F10gp metastasis to the lungs using a triplex Q-PCR method, which detects the expression of the melanoma genes GP100 and tyrosinase-related protein 2 (TRP-2) relative to the reference gene glyceraldehyde-3-phosphate dehydrogenase (GAPDH)." (PMID 24498205, 2014). "Interestingly, whereas hydrogen peroxide led to a decrease in GAPDH enzyme activity in both cell lines, CNP incubation only led to a loss of activity in melanoma cells but not in the normal melanocytes." (PMID 38512909, 2024). "Even though we macrodissected all skin and melanoma sections before RNA extraction and only included RNA samples with comparable RIN values, we observed a large degree of variation in gene expression levels of ACTB and GAPDH across the 13 melanoma samples investigated." (PMID 31567589, 2020). "However, whether orally administered HA affects the GAPDH activity of extraintestinal tumors, including melanoma, and exhibits antitumor functions has not been elucidated." (PMID 35459092, 2022). "We also examined the expression of ACTB and GAPDH in non-cancerous epidermal tissue samples taken from the melanoma patients, and we found that the expression of ATCB and GAPDH vary substantially between the normal epidermal tissue samples as well." (PMID 31567589, 2020).
viral infection (42 papers, 2007 to 2025). "By normalizing the Cq value of ShaV antigenome with the Cq value of monkey GAPDH, the efficiency of virus infection was found to be reduced in α2,3-linked sialic acid-cleaved cells." (PMID 35924912, 2022). "Higher levels of GAPDH DNA were detected in the supernatant of infected cells compared with uninfected cells, probably due to cytotoxic effects and cell death caused by virus infection." (PMID 29093211, 2017). "Small shifts in polyribosome density were observed in RhCMV infection for both HC and GAPDH mRNA, suggesting virus infection causes a slight reduction of ribosomal occupancy on cellular transcripts." (PMID 18833297, 2008). "RSAD2 is a direct modulator of GAPDH activity and is typically activated by interferon in immune cells during viral infection." (PMID 39334961, 2024). "Recent research indicates that phosphorylating GAPDH exhibits various moonlighting functions, contributing to plant growth and development, autophagy, drought tolerance, salt tolerance, and bacterial/viral diseases resistance." (PMID 38745922, 2024). "Our analyses suggest that inhibition of GAPDH by the cellular innate immune response primes a broad‐spectrum immune response to viral infection." (PMID 33185982, 2021). "Virus infection slightly upregulated GE of ZNT5/GAPDH compared to respective controls and increased GE of HMA3/GAPDH in Zn10 infected leaves." (PMID 32582260, 2020). "Immunoblotting for VACV protein D8 showed that the virus infections were equivalent and immunoblotting for GAPDH showed equal loading of samples." (PMID 27907166, 2016). "For example transcripts of the classical reference genes, beta actin (β-actin) and glyceraldehyde 3-phosphate dehydrogenase (GAPDH), varied greatly during bacterial and viral infection." (PMID 25313905, 2014). "Upon drug treatments, identical relative amounts of host markers, such as tubulin and GAPDH, and viral infection markers, such as NSP5 and VP2 were detected by immunoblotting." (PMID 23110139, 2012). "Conversely, APR, TUB, SAMD, ACT and GAPDH showed relatively low expression stability in leaf tissues of N. benthamiana during viral infections." (PMID 23029521, 2012). "In this study, we show that GAPDH is incorporated into the virions and the suppression of GAPDH packaging inside the virions enhances viral infection owing to the high reverse transcription efficiency." (PMID 23237566, 2012). "In relation to the housekeeping gene, GAPDH, cPMLΔ5&6 transcripts were increased 3- to 4- fold during viral infection." (PMID 18509536, 2008). "Many studies have reported that experimental conditions, such as dietary restriction, metals, viral infection, and herbicides, influence the expression of reference genes that have traditionally been considered as reference genes (e.g., GAPDH, HPRT1, and 18S rRNA)." (PMID 37780581, 2023). "Based on these analyses, we propose that inhibiting GAPDH in individuals with deteriorated cellular innate immune response like elderly might help in treating viral diseases such as COVID‐19." (PMID 33185982, 2021). "However, ACTB and GAPDH remain widely used in the studies of host gene response to virus infections, including influenza viruses." (PMID 23043930, 2012). "Recently, accumulated evidence showed that in HBV-related hepatocellular carcinoma or viral infections, beta-actin and GAPDH are unsuitable controls in quantitative mRNA expression or Western blot analysis due to variations in expression, though there are controversial observations." (PMID 20529248, 2010). "This suggests a potential impact of NeST1-, GAPDH-and ficolin-3-TLR4 interactions on viral infections." (PMID 36070318, 2022). "As expected, in comparison with single reference gene, the normalization of OsPR1b using UBQ 10 + GAPDH and UBC + Actin1, respectively, resulted in significant increase in transcript levels under virus infection conditions." (PMID 26497487, 2015).
viral infection (continued). "Twenty-four hours after the virus infection, the FANCC mRNA level was found to be upregulated, while the GAPDH mRNA level remained unchanged." (PMID 19936073, 2007). "Overall, the results suggest that although GAPDH is widely used as a loading control, it is not a bona fide housekeeping gene, and its use and interpretation should be carefully monitored in viral infection studies." (PMID 38594438, 2024). "Glyceraldehyde-3-phosphate dehydrogenase (GAPDH), a glycolytic enzyme, has emerged as a multifunctional protein in several non-metabolic processes and is increased in several plant species following viral infection." (PMID 33721115, 2021). "However, the levels of house keeping control gene (GAPDH) were similar at all the time points, suggesting that the enhanced levels of SERCA2 expression were related to viral infection." (PMID 30814986, 2019). "Moreover, both the ratio of LC3-II/GAPDH and the expression of viral NS3 protein increased with increasing time of viral infection." (PMID 29762492, 2018). "SOCS3, relative to GAPDH housekeeping reference, was not changed by either the treatments or virus infection at the 24 hr time point." (PMID 24098792, 2013). "We selected 16 candidate reference genes, some of which were commonly used as normalisation factors in qRT–PCR analysis, such as GAPDH, 18S, EF1α, ACT and TUB, and other genes showed a high expression stability in plant species under viral infection or other experimental settings." (PMID 23029521, 2012). "Therefore, GAPDH is important in some viral infections, but we do not know how GAPDH interacts with VHSV nor the biological significance of this interaction." (PMID 31040842, 2019). "Hence, GAPDH upregulation by IFN-I may contribute to apoptosis induction and TNFα repression in R. aegyptiacus, which could represent novel mechanisms for the prevention of excessive inflammation during viral infections." (PMID 34737406, 2021). "Consistently, our study also revealed the altered expression of GAPDH, AGO2, and actins upon viral infections, suggesting that these are not suitable as reference genes in studies of viral infection." (PMID 36840204, 2023). "However, no RPS16 and GAPDH bands were detected in the precipitated samples, indicating that RALY interacts with the FMDV RNA during viral infection." (PMID 38323828, 2024).